TUBA4B (tubulin alpha 4b)
Description:
Tubulin is the major constituent of microtubules, a cylinder consisting of laterally associated linear protofilaments composed ofalpha- and beta-tubulin heterodimers.
Synonyms: TUBA4; FLJ13940
Tractability: PROTAC: ubiquitination databases record sites on it.
Gene: Protein-coding gene on chromosome 2 (219,253,243 to 219,272,197, forward strand). Ensembl gene ENSG00000243910.
Subcellular location: Cytoplasm, cytoskeleton
Pathways (Reactome):
Cell Cycle: EML4 and NUDC in mitotic spindle formation; Mitotic Prometaphase; Recruitment of NuMA to mitotic centrosomes; Resolution of Sister Chromatid Cohesion; Sealing of the nuclear envelope (NE) by ESCRT-III; Separation of Sister Chromatids; The role of GTSE1 in G2/M progression after G2 checkpoint
Vesicle-mediated transport: COPI-dependent Golgi-to-ER retrograde traffic; COPI-independent Golgi-to-ER retrograde traffic; COPI-mediated anterograde transport; Gap junction assembly; Microtubule-dependent trafficking of connexons from Golgi to the plasma membrane; Translocation of SLC2A4 (GLUT4) to the plasma membrane
Metabolism of proteins: Carboxyterminal post-translational modifications of tubulin; Formation of tubulin folding intermediates by CCT/TriC; Post-chaperonin tubulin folding pathway
Immune System: MHC class II antigen presentation; PKR-mediated signaling
Neuronal System: Activation of AMPK downstream of NMDARs; Assembly and cell surface presentation of NMDA receptors
Signal Transduction: RHO GTPases Activate Formins; RHO GTPases activate IQGAPs
Autophagy: Aggrephagy
Cellular responses to stimuli: HSP90 chaperone cycle for steroid hormone receptors (SHR) in the presence of ligand
Developmental Biology: Recycling pathway of L1
Disease: HCMV Early Events
Hemostasis: Kinesins
Gene Ontology:
Molecular function: GTPase activity; GTP binding; structural constituent of cytoskeleton
Biological process: cytoskeleton organization; microtubule-based process
Cellular component: cytoskeleton; microtubule; microtubule cytoskeleton
Genetic constraint (gnomAD): Loss-of-function variants: 6 observed, 10.67 expected, observed/expected ratio (o/e) 0.56, 90% interval 0.31 to 1.11. The upper end of that interval is the gene's LOEUF score, 1.11, which puts it in group 4 of 6, group 1 being the genes least tolerant of losing a copy. Missense variants: 121 observed, 160.29 expected, observed/expected ratio (o/e) 0.75, 90% interval 0.65 to 0.88. Synonymous variants: 57 observed, 62.98 expected, observed/expected ratio (o/e) 0.91, 90% interval 0.73 to 1.13.
Homologues: Orthologues: chimpanzee TUBA4B (95% identical), dog TUBA1C (74% identical), zebrafish tuba2 (73% identical), Caenorhabditis elegans mec-12 (71% identical). Paralogues in human: TUBA1B (73% identical), TUBA1C (73% identical), TUBA1A (72% identical), TUBA4A (71% identical), TUBA3C (70% identical), TUBA3D (70% identical), TUBA8 (70% identical), TUBA3E (69% identical), TUBAL3 (55% identical), TUBB (37% identical), TUBB4B (37% identical), TUBB2A (36% identical), and 11 more.
Diseases named in the same sentence as TUBA4B in open-access papers:
TUBA4B is named in the same sentence as 7 diseases in open-access papers, as found by Europe PMC text mining. Sharing a sentence is not in itself a finding about the gene and the disease. The quoted sentences say what the papers report.
non-small cell lung carcinoma (2 papers, 2018 to 2019). A group of at least three distinct histological types of lung cancer, including non-small cell squamous cell carcinoma, adenocarcinoma, and large cell carcinoma. "LncRNA TUBA4B has been reported to serve as a new predictor for prognosis and modulate cell viability in non-small-cell lung cancer." (PMID 31558162, 2019).
gastric cancer (1 paper, 2020). A primary or metastatic malignant neoplasm involving the stomach. "It has also been reported that lncRNA HOXA11-AS (HOXA11 antisense RNA) and TUBA4B (tubulin alpha 4b) are tightly correlated with the tumor size, TNM stage, and lymph node metastasis of gastric cancer." (PMID 32460771, 2020).
cancer (3 papers, 2019 to 2022). A tumor composed of atypical neoplastic, often pleomorphic cells that invade other tissues. "Similar to SCN4B, the low expression of Tubulin alpha 4b (TUBA4B) has also been shown to be significantly associated with poor prognosis of cancer patients." (PMID 33902636, 2021). "For instance, tubulin alpha 4b (TUBA4B) was significantly decreased in cancer tissues compared with adjacent normal specimens." (PMID 31632195, 2019). "Overall, the study suggested that low levels of TUBA4B are significantly associated with short OS, DFS, and RFS in cancers and that TUBA4B could therefore be a BC biomarker." (PMID 35740618, 2022). "Low TUBA4B expression was closely correlated with pathological grade, LNM, OS, DFS, and RFS in cancer patients and can be a novel biomarker for the prognosis of various cancers." (PMID 31632195, 2019).
tumor (2 papers, 2018 to 2020). "As result, the α-tubulin isoforms TUBA1B, TUBBA1A and TUBA1C had the highest mRNA expression levels, while TUBA4B and TUBA8 had the lowest expression level among the tubulin isoforms in all the tumor samples." (PMID 30126203, 2018).
TUBA4B also shares sentences with these, for which no sentence is quoted: Macrothrombocytopenia (1 paper); ovarian carcinoma (1); renal carcinoma (1).